HSD17B13 (hydroxysteroid 17-beta dehydrogenase 13)
Description:
Plays a pivotal role in hepatic lipid metabolism. In vitro, it catalyzes the oxidation of a variety of lipid substrates, including 17beta-estradiol, retinol, retinal, and leukotriene B4. [Isoform 2]: Has retinol/retinal dehydrogenase activity in vitro. [Isoform 1]: Does not have retinol/retinal dehydrogenase activity in vitro.
Synonyms: SCDR9; SDR16C3; HMFN0376; FLDP; NIIL497
Tractability: Small molecule: a structure with a bound ligand is known. Antibody: UniProt predicts a signal peptide or a membrane-spanning region.
Target class: Enzyme; Oxidoreductase
Chemical probes: BI-3231 (high quality)
Gene: Protein-coding gene on chromosome 4 (87,303,789 to 87,322,945, reverse strand). Ensembl gene ENSG00000170509.
Subcellular location: Lipid droplet (Isoform 2); Endoplasmic reticulum; Cytoplasm (Isoform 1)
Subcellular location (Human Protein Atlas): Vesicles; Golgi apparatus
Pathways (Reactome):
Metabolism: Lipid particle organization
Gene Ontology:
Molecular function: all-trans-retinol dehydrogenase (NAD+) activity; estradiol 17-beta-dehydrogenase [NAD(P)+] activity; protein binding; lipid transfer activity; oxidoreductase activity, acting on the CH-OH group of donors, NAD or NADP as acceptor; steroid dehydrogenase activity; retinal dehydrogenase (NAD+) activity
Biological process: positive regulation of lipid biosynthetic process; lipid droplet organization; intermembrane lipid transfer
Cellular component: cytoplasm; lipid droplet; cytosol; endoplasmic reticulum
Genetic constraint (gnomAD): Loss-of-function variants: 16 observed, 21.13 expected, observed/expected ratio (o/e) 0.76, 90% interval 0.51 to 1.15. The upper end of that interval is the gene's LOEUF score, 1.15, which puts it in group 5 of 6, group 1 being the genes least tolerant of losing a copy. Missense variants: 280 observed, 277.14 expected, observed/expected ratio (o/e) 1.01, 90% interval 0.92 to 1.12. Synonymous variants: 112 observed, 105.83 expected, observed/expected ratio (o/e) 1.06, 90% interval 0.91 to 1.24.
Homologues: Orthologues: chimpanzee HSD17B13 (98% identical), macaque HSD17B13 (96% identical), rabbit HSD17B13 (87% identical), guinea pig HSD17B13 (84% identical), mouse Hsd17b13 (81% identical), pig HSD17B13 (77% identical), rat Hsd17b13 (76% identical), tropical clawed frog hsd17b13 (61% identical). Paralogues in human: HSD17B11 (63% identical), RDH10 (41% identical), SDR16C5 (40% identical), DHRS3 (33% identical), RDH12 (25% identical), RDH16 (24% identical), HSD17B12 (24% identical), HSD17B6 (24% identical), RDH11 (23% identical), HSD17B4 (22% identical), SDR9C7 (22% identical), HSD11B2 (21% identical), and 13 more.
Diseases named in the same sentence as HSD17B13 in open-access papers:
HSD17B13 is named in the same sentence as 46 diseases in open-access papers, as found by Europe PMC text mining. Sharing a sentence is not in itself a finding about the gene and the disease. The quoted sentences say what the papers report.
liver disease (34 papers, 2019 to 2026). "Studies of the human genetic variants of HSD17B13 (protective against severe liver disease) have reported an increase in phospholipids including PC 34:3." (PMID 40016916, 2025). "HSD17B13 has gained attention in recent years due to its association with liver disease, particularly MASLD and its more severe form, steatohepatitis." (PMID 38673981, 2024). "Recent results showed that 17-beta-hydroxysteroid dehydrogenase type 13 (HSD17B13) is associated with liver diseases, but these conclusions are controversial." (PMID 35628360, 2022). "Recently, mitochondrial amidoxime reducing component 1 (MTARC1) rs2642438 and hydroxysteroid 17-beta dehydrogenase 13 (HSD17B13) rs72613567 polymorphisms were shown to have protective effects on liver diseases." (PMID 36555467, 2022). "We collected clinical, demographic, and biochemical data, and we performed a genotyping analysis for common variants previously associated with liver disease risk (HSD17B13 rs72613567:TA and PNPLA3 rs738409)." (PMID 36233142, 2022). "Another study investigated the association between HSD17B13 and liver disease and showed that the HSD17B13 rs72613567 TA variant reduced the risks of alcohol-, NAFLD-, and hepatitis C-related cirrhosis and alcohol-related HCC." (PMID 33922278, 2021). "Although the research on the relationship between HSD17B13 rs72613567: TA allelic variant and liver disease has attracted the attention of many researchers, the conclusion is not clear." (PMID 34930143, 2021). "To assess the association of HSD17B13 rs72613567:TA allelic variant with liver disease, we performed the current review and meta-analysis." (PMID 34930143, 2021). "There are two main types of HSD17B13 gene mutations associated with liver disease including rs72613567 and rs6834314." (PMID 34930143, 2021). "In the meta-analysis of HSD17B13 rs72613567: TA allelic variant and liver disease susceptibility, the Egger regression analysis suggested that obviously publication bias existed in HCC patients compared with healthy controls." (PMID 34930143, 2021). "Nowadays, some studies have shown that hydroxysteroid 17-β dehydrogenase family 13 (HSD17B13) rs72613567:TA allelic variant is associated with liver disease." (PMID 34930143, 2021). "From this targeted exome association analysis, the protein-truncating variant in HSD17B13 (rs72613567) was found to confer lower odds across all categories of liver disease and provide protection against liver fibrosis in an allele dose-dependent manner." (PMID 34950105, 2021). "In order to unify these differences, a meta-analysis of published research was conducted to comprehensively assess the relationship between HSD17B13 rs72613567: TA allelic variant and liver disease." (PMID 34930143, 2021). "The association between HSD17B13 variant and reduced risk for advanced liver disease has also been shown in viral, alcoholic, portal hypertension, and in Wilson’s disease." (PMID 32443539, 2020). "Silymarin/silybin regulates a significant number of these lipid metabolic genes, including iPLA2/PLA2G6, ATGL/PNPLA2, PLD1, LPIN2, and by trend PNPLA3 (which is a major genetic risk factor for MAFLD 131) and HSD17B13, counteracting the observed dysregulation in liver diseases." (PMID 39897559, 2025). "Thus, together with the human gene variant data on HSD17B13 and liver disease, we were attracted to investigating this protein further." (PMID 40016916, 2025). "However, the exact mechanisms by which HSD17B13 variants impact liver disease are still under investigation." (PMID 38673981, 2024). "Similarly, the HSD17B13-CD244 interaction introduces a novel aspect to LUAD pathogenesis, given HSD17B13’s known association with liver diseases and its potential druggability in lung cancer." (PMID 39092217, 2024). "Research suggests that genetic variants of HSD17B13 may influence liver fat accumulation and the progression of liver disease." (PMID 38673981, 2024).
liver disease (continued). "Because loss of function HSD17B13 variants are protective against NASH, small molecule HSD17B13 inhibitors may serve as oral medications for liver diseases." (PMID 37620305, 2023). "On the other hand, the loss of function of HSD17B13 caused by genetic variations has positive effects in hepatic diseases, and HSD17B11 could be a target for the treatment of pancreatic diseases." (PMID 34503201, 2021). "Genetic variants in PNPLA3 and HSD17B13 may be one of the targets to be knocked down by RNA interference and antisense oligonucleotide therapies, leading to the prevention of the development to severe liver diseases in patients with MASLD/MASH." (PMID 40507973, 2025). "Mislocalization of certain LD-targeted membrane proteins, including HSD17B13 and PNPLA3, is implicated in metabolic dysfunction-associated steatotic liver disease." (PMID 42191894, 2026). "Some variants located in HSD17B13 and MTARC1 offer protective effects, reducing the risk of severe liver disease despite comorbidities such as obesity, and can mitigate the harmful effects of these risk alleles." (PMID 41772607, 2026). "The study presented herein addresses this gap by investigating the lipidomic profiles of liver obtained from aged Hsd17b13 gene knockout (KO) mice, aiming to provide new insights into the role of this enzyme in age-related liver disease." (PMID 40559377, 2025). "This study evaluated the distribution of PNPLA3 rs738409, TM6SF2 rs58542926, and HSD17B13 rs6834314 and overall survival of HCC patients with metabolic dysfunction-associated steatotic liver disease (MASLD-HCC) and viral-related HCC (VIRAL-HCC)." (PMID 40725464, 2025). "A recent structural analysis has elucidated how these protective variants disrupt the anchoring mechanisms of droplet-associated proteins to membranes, offering a therapeutic angle targeting HSD17B13 for these liver diseases." (PMID 39744163, 2025). "HSD17B13, predominantly expressed in hepatocytes, occupies a critical niche in liver disease etiology (Lindén and Romeo, 2023)." (PMID 39496977, 2024). "We demonstrated that the high expression of HSD17B13 facilitated the occurrence and development of early liver diseases." (PMID 35628360, 2022). "Both rs72613567T>TA in HSD17B13 and rs2642438G>A in MTARC1 were originally identified as GWAS‐significant risk‐reducing loci for liver disease in adults." (PMID 35411667, 2022). "To verify the specificity of HSD17B13 expression in liver diseases, we detected their expression in a palmitate-induced cell model." (PMID 35628360, 2022). "Despite the number of studies on HSD17B13 and liver disease in American and European countries, to our knowledge there are no data available so far in Asian countries." (PMID 32443539, 2020). "Growing evidence implicates HSD17B13 in the pathogenesis of multiple liver diseases." (PMID 40559377, 2025). "The role of HSD17B13 in age-related liver diseases remains understudied." (PMID 40559377, 2025). "Furthermore, the down-regulation of the more highly expressed HSD17B13 by shRNA attenuated liver diseases." (PMID 35628360, 2022). "In the early stages of liver diseases, HSD17B13 expression is enhanced." (PMID 35628360, 2022). "In conclusion, genetic variants in PNPLA3, TM6SF2, MBOAT7, and HSD17B13 do not seem to impact the short-term regression of portal hypertension." (PMID 33917196, 2021). "iPS cells could help uncover the protective mechanism of the HSD17B13 genetic variant and expose a therapeutic target for FLD, solving the biggest hurdle in liver disease of this era." (PMID 34208839, 2021). "Recently, the Hydroxysteroid 17-Beta Dehydrogenase 13 (HSD17B13) rs7261356 and the Protein Phosphatase 1 Regulatory Subunit 3B (PPP1R3B) rs4841132 have been shown to confer protection against liver disease, at least in at-risk individuals, instead." (PMID 32443539, 2020).
liver disease (continued). "The HSD17B13 association is consistent with a recent study reporting that a loss-of-function variant associated with decreased levels of ALT and aspartate aminotransferase (AST) and reduced the risk of liver disease and progression from NAFLD to NASH." (PMID 30978214, 2019). "In a Japanese MASLD cohort, carriers of the HSD17B13 rs6834314 G allele exhibited a diminished impact of the PNPLA3 rs738409 GG genotype on the development of advanced fibrosis, further supporting a modifying role of HSD17B13 in genetic susceptibility to liver disease." (PMID 41001677, 2025). "Therefore, genetic variants in PNPLA3/TM6SF2/MBOAT7/HSD17B13 do not impact the regression of portal hypertension and clinical outcomes in patients with pre-treatment ACLD after CHC cure." (PMID 33917196, 2021). "Our data are consistent with those reported for other ethnicities and, together with them, underline the potential of HSD17B13 as a therapeutic target to treat liver disease irrespective of ethnicity, and its role in the genetic susceptibility to chronic liver disease." (PMID 32443539, 2020). "The identification of specific drugs targeting HLA-DRB5, GJB3, HSD17B13, and CD244 for various indications, such as cancer, metabolic diseases, and liver disorders, further strengthens their potential as therapeutic targets in LUAD." (PMID 39092217, 2024). "BI-3231 (compound 45) is the first potentand selective chemical probe reported for HSD17B13, a potential newtarget for the treatment of NASH and other liver diseases." (PMID 36727857, 2023). "Genome‐wide interaction study identified 9 ALT and 12 AST independent associations significantly modified by body mass index (BMI), including several previously reported potential liver disease therapeutic targets, for example, PNPLA3, HSD17B13, and MARC1." (PMID 34184762, 2021). "Moreover, the impact of HSD17B13 on the clinical course of liver disease could be stage dependent." (PMID 34076851, 2021). "HSD17B13 and PNPLA3 have both been shown to localize to lipid droplets, but it is not yet understood to what extent the alteration in TG composition is a primary contributor to the severity of liver disease." (PMID 35411667, 2022).
Cirrhosis (28 papers, 2018 to 2025). A chronic disorder of the liver in which liver tissue becomes scarred and is partially replaced by regenerative nodules and fibrotic tissue resulting in loss of liver function. "In summary, our findings suggest that SNPs in PNPLA3 and HSD17B13 are associated with MASLD-related cirrhosis development." (PMID 40995436, 2025). "A different set of six microRNAs (miR-19a, miR-26a, miR-101, miR-151-3p, miR-221, and miR-301) showed positive correlation (ranging from 0.32 to 0.51, p < 0.05) with rs10433937:HSD17B13 gene variant, associated with the risk of cirrhosis." (PMID 37887024, 2023). "HSD17B13 [TA] (hydroxysteroid 17-beta dehydrogenase 13) encodes a hepatic lipid droplet protein and is associated with a protective effect against cirrhosis in fatty liver diseases due to NAFLD or alcohol." (PMID 33804302, 2021). "This analysis revealed that variants in MARC1 and HSD17B13 were associated with both cirrhosis and cT1 values." (PMID 34950105, 2021). "Conversely, HSD17B13 variants demonstrate a protective effect against cirrhosis and HCC." (PMID 40995436, 2025). "Of the 36 cirrhosis variants, we identified protein-altering variants in LD (r2 > 0.8) with the lead variant at 16 loci, including 3 splice variants in HSD17B13 (rs72613567, c.812+2dupT), MAMSTR (rs11666792, c.219+3G>A) and PYGB (rs2261790, c.1518+6T>C)." (PMID 38632349, 2024). "HSD17B13 gene encodes for an enzyme that concentrates lipid droplets in hepatocytes: loss-of-function variants in HSD17B13 result in higher protection against liver inflammation, cirrhosis, and HCC (Trépo & Valenti, 2020; Choudhary and Duseja, 2021)." (PMID 35250588, 2022). "In 2018, the splice variant (rs72613567:TA) in HSD17B13 gene, encoding the hydroxysteroid 17-β dehydrogenase 13, was discovered to be associated with protection against histological steatohepatitis, fibrosis and cirrhosis in both NAFLD and ALD patients." (PMID 34680476, 2021). "Of those, we found that rs72613567 in HSD17B13 and known risk variants in SERPINA1 (p.Glu366Lys) and HFE (p.Cys282Tyr) exhibited stronger effects on cirrhosis than on NAFLD." (PMID 38632349, 2024). "The progression to HCC is influenced by factors such as the severity of fibrosis and the presence of cirrhosis, with specific genetic variants like PNPLA3 and HSD17B13 contributing to the increased risk." (PMID 39617908, 2024). "Other variants, such as those in HSD17B13 and MAMSTR, were found to have larger effects on cirrhosis compared with NAFLD, indicating a more dominant role in the progression to clinically advanced stages of chronic liver disease." (PMID 38632349, 2024). "The predictive model for future cirrhosis development (AUC of 0.836 95% CI: 0.769–0.904) accounted for age at onset of at-risk alcohol consumption and the number of PNPLA3 and HSD17B13 variant alleles." (PMID 37626629, 2023). "Another study reported that the combination of PNPLA3, TM6SF2 and HSD17B13 predicted NASH-cirrhosis and HCC in general population settings." (PMID 36266438, 2022). "On the other hand, LEPR is only associated with ALT levels and histologically defined NASH, and HSD17B13 is associated with NASH and cirrhosis." (PMID 34950105, 2021). "Most recently, exome-wide sequencing has identified the rs72613567:TA variant within hydroxysteroid 17-beta dehydrogenase 13 (HSD17B13), which was associated with a decreased risk of alcoholic liver disease, NASH, alcoholic cirrhosis, and NASH cirrhosis." (PMID 30355853, 2018). "Interestingly, the majority of SNPs identified as risk factors for alcohol-associated cirrhosis in recent GWAS reside in/around the genes related to lipid metabolism and lipid droplet biology (PNPLA3, HSD17B13, FAF2 and TM6SF2)." (PMID 37887024, 2023). "A common splice variant in HSD17B13 (rs72613567:TA) was recently found to be associated with a reduced risk of developing chronic liver disease in NAFLD patients and a reduced risk of progression to advanced fibrosis and cirrhosis." (PMID 36233142, 2022).
Cirrhosis (continued). "A variant in the 17B-hydroxysteroid dehydrogenase 13 (HSD17B13) gene has been reported to protect against NAFLD, progression from hepatic steatosis to steatohepatitis (NASH), alcoholic liver disease (ALD), and associated liver fibrosis/cirrhosis." (PMID 34076851, 2021). "We examined the association of all-cause cirrhosis with six genetic variants previously reported to be associated with alcoholic or non-alcoholic cirrhosis: PNPLA3 I48M, TM6SF2 E167K, MBOAT7 rs641738, HSD17B13 rs72613567, HFE C282Y and SERPINA1 E366K." (PMID 32282858, 2020). "Analysis of biopsy-diagnosed samples may also clarify whether, like HSD17B13, MARC1 has differing associations with fatty liver, non-alcoholic steatohepatitis and cirrhosis." (PMID 32282858, 2020). "No statistical significance was observed for the OR of SNPs in MBOAT7, HSD17B13, and TM6SF2 in MASLD-related cirrhotic HCC compared with cirrhosis." (PMID 40995436, 2025). "Higher HSD17B13 expression was significantly observed in the livers with NASH or cirrhosis, with the samples demonstrating IHC scores of 67.85 ± 1.37 in NASH and of 68.89 ± 1.71 in cirrhosis compared to the scores of 49.74 ± 4.13 found in normal livers." (PMID 35628360, 2022). "Since the rs738409 PNPLA3 and rs72613567 HSD17B13 but not the rs58542926 TM6SF2 were significantly associated with the development of liver cirrhosis over time, we delineated a predictive model for cirrhosis development over time." (PMID 37626629, 2023). "The lack of association of MARC1 p.A165T and HSD17B13 rs72613567 with CAD (in contrast to PNPLA3 and TM6SF2) suggests that pharmacologic treatment of cirrhosis and hepatic steatosis may not universally cause excess cardiovascular risk." (PMID 32282858, 2020).